CCND1 (cyclin D1)
Diseases named in the same sentence as CCND1 in open-access papers (continued):
Sharing a sentence is not in itself a finding about the gene and the disease.
colon carcinoma (continued). "To clarify the mechanism of pterostilbene activity against colon cancer cells, we also evaluated changes in the expression of the cell cycle regulatory genes CCND1 and CDKN1A." (PMID 36674631, 2023). "Garcinol has been previously found to reduce the expression of cyclin D1 in endometrial, gastric, and colon cancers, as well as inhibit the expression of mTOR in human prostate cancer cells and xenograft." (PMID 37577271, 2023). "To gain additional mechanistic insights, we examined the effects of βPix deficiency on several genes associated with colon cancer progression; c-MYC, CCND1, and PTGS2, which encode c-Myc, β-catenin, and cyclooxygenase-2." (PMID 37805544, 2023). "In normal colonic mucosa, adenoma, and adenocarcinoma in colon tumors, Cyclin D1 is highly expressed." (PMID 35879795, 2022). "The increased expression of PPAR-β/δ mRNA in colon cancers has been attributed to APC-β-catenin-TCF4-mediated transcription, similar to the well-known target gene β-catenin-TCF4 CCND1, which encodes cyclin D1." (PMID 35203272, 2022). "Many studies revealed the association between STAT3 activation, up-regulated expression of Cyclin D1, c-Myc, and survivin, and cell cycle progression in colon cancers." (PMID 35056682, 2022). "After 14 days of treatment, there was an increase in the expression of Myc and cyclin D1 in colon cancer tissue." (PMID 35956766, 2022). "A previous study confirmed that miR-365 is downregulated in colon cancer tissues, is involved in tumor progression, and regulates cancer cell behavior by targeting cyclin D1 and Bcl-2." (PMID 35682793, 2022). "SIRT6 can not only upregulate the expression of tumor suppressors phosphatase and tensin (PTEN), and phosphatidylinositol-4,5-biphosphate (PIP2), but also can downregulate AKT1, mTOR, cyclin D1, and c-myc to inhibit the progression of colon cancer." (PMID 35172823, 2022). "Downregulation of the Wnt/β-catenin pathway and related genes (cyclin D1 and survivin) was involved in quercetin-induced apoptotic episodes in colonic cancer cells." (PMID 36557939, 2022). "In terms of cell-cycle regulation, it was previously found that EGC kept Lovo colon cancer cells in the G1 phase and inhibited the expression of cyclin D1 and CDK4 in tumor cells." (PMID 36500365, 2022). "Several studies have shown the arrest of cell proliferation in the invasion front of colonic carcinomas characterized by low levels of cyclin D1, β-catenin, and Ki-67." (PMID 34071030, 2021). "For instance in SW620 colon carcinoma cells, NaBu downregulated β-catenin-dependent expression of the Tcf-TK, matrilysin, and cyclin D1 promoters." (PMID 34681943, 2021). "In line, CCND1 amplification has been reported to be associated with a CpG island methylator phenotype (CIMP)-high status in breast and colon cancer." (PMID 34933671, 2021). "There are several studies reporting a positive correlation between Cyclin D1 over-expression and malignancies including colon cancer." (PMID 33883985, 2021). "Treatment of colon cancer cell lines with rhIL-23 increased the expression of the cell proliferation marker cyclin D1 in Caco2 cells at all doses, however, in HCT116 only 40 and 100 ng doses increased the expression of cyclin D1." (PMID 34680308, 2021). "The expression of cyclin D1 and cyclin E significantly increased in all BR colon cancer cells compared to that in their respective PT colon cancer cells." (PMID 34829834, 2021).
colon carcinoma (continued). "CDCA3 promotes cell proliferation by activating the NF-κB/cyclin D1 axis in colon cancer, which is probably a potential prognostic biomarker in gastric cancer." (PMID 34699322, 2021). "The protein and mRNA expression levels of SDF-1 and CXCR4 and their downstream proteins cyclin D1 and c-myc in the tumour tissues of mice with colon cancer were detected by Western blot." (PMID 34531745, 2021). "Meanwhile, the expression of CCND2 has been reported to be increased in chronic B‐cell malignancies and CCND1 elevated in colon cancer, and there is a close relation of CCND1 and CCND2 with clinical results, TNM staging, and metastasis." (PMID 33473276, 2021). "To determine the Wnt signaling target genes, we also assessed the c-myc and cyclin D1 that control cellular transcription and cell cycle regulation in colon cancer cells." (PMID 34536148, 2021). "Based on this rationale, we analyzed the protein levels of CDK2/4 and cyclin D1/E in colon cancer cells." (PMID 33669811, 2021). "The high expression of cyclin D1 and Ki67 is related to a significant shorter overall survival in colon cancer patients." (PMID 33795755, 2021). "ZIPK increases the expression of Wnt pathway downstream gene cyclin D1 and survivin and enhances colon cancer cell SW480 growth." (PMID 34375503, 2021). "They concluded that PAC exhibits anti-colon cancer properties that have potential, by targeting cyclin D1 and suppressing JAK2/STAT3, AKT/mTOR and MEK/ERK signaling pathways as well as their common downstream effector which is cyclin D125." (PMID 34083581, 2021). "In this regard, Dimethylfumarate also has anti-tumorigenic properties on colon cancer cells and sensitizes cells to radiation through apoptosis, which is accompanied by cell cycle arrest in the G0/G1 phase and reduces cyclin D1 expression." (PMID 34536148, 2021). "In this study, we identified six cyclin genes (CCNA2, CCNB1, CCND1, CCNE1, CCNF, and CCNJL) that are potential diagnostic biomarkers of colon cancer." (PMID 33996604, 2021). "In our study, ectopic expression of Zic2 promoted colon cancer proliferation by activating cyclin D1 transcription, in addition to cell cycle transition from G0/G1 to S phase in vitro." (PMID 34099631, 2021). "Overexpression of miR-449a induces cell cycle arrest in human bladder cancer cells and suppresses cell proliferation through the regulation of cyclin D1 expression in colon cancers." (PMID 34830336, 2021). "Reports from cancer studies demonstrated that NDRG2 inhibits c-Myc expression by suppressing the expression of β-catenin and reduces c-Jun phosphorylation and cyclin D1 expression resulting in suppression of cell proliferation in human colon carcinoma cells." (PMID 32433643, 2020). "Several studies have shown that the expression of cyclin D1 was downregulated by TZDs in colon cancer, breast cancer, and prostate cancer as part of the mechanism for causing G1 cell-cycle arrest and growth inhibition of cancer cells." (PMID 32170185, 2020). "Z-Ajoene repressed β-catenin response transcriptional activity, intracellular β-catenin levels, and its representative target protein levels (c-Myc and cyclin D1) in SW480 colon cancer cells." (PMID 32041324, 2020). "The inhibition of SNHG7 in HT29 colon cancer cells stimulates cell apoptosis by inactivating K-ras/ERK/cyclin D1 signaling." (PMID 33246471, 2020). "SNHG1 accelerates cell proliferation via upregulating β-catenin, c-Myc and cyclin D1 protein levels in colon cancer cells." (PMID 33246471, 2020). "All these results indicated IGF2BP3 repressed S phase as well as the proliferation of colon cancer by reading m6A modification of CCND1." (PMID 32993738, 2020). "In summary, we demonstrated m6A reader IGF2BP3 regulated cell cycle and angiogenesis of colon cancer via reading m6A modification of CCND1 and VEGF respectively." (PMID 32993738, 2020).
colon carcinoma (continued). "At the molecular level, A1874 is able to induce BRD4 protein degradation and the downregulation of BRD-dependent genes (c-Myc, Bcl-2 and cyclin D1) in colon cancer cells." (PMID 32978368, 2020). "Nevertheless, EGCG has been demonstrated to play a potential role in human colon cancer prevention inhibiting AP-1, c-fos, cyclin D1 promoters, and NF-κB activity in four different human colon cancer cell lines, with an IC50 value of about 20 μg/mL." (PMID 31979082, 2020). "Although LOC441461-knockdown-induced suppression of CCNB1 was observed in all colon cancer cells, the suppression of CCND1 and CDK4 was observed in SW620, DLD-1, and LS174T cells but not LoVo cells." (PMID 33126743, 2020). "Cell viability of colon cancer cells used in the study (MCA38) was seen to decrease after the reduction in cyclin D1 expression." (PMID 33312942, 2020). "Western blot analysis of colon tumors confirmed strongly reduced levels of pSTAT3 in bazedoxifene‐treated mice, coinciding with reduced Bcl‐xL, cyclin D1, and survivin expression." (PMID 30885958, 2019). "Curcumin as an anticancer agent has been reported to induce apoptosis, reduce survival and able to down-regulate Bcl-2, VEGF, cyclin D1, pro-oncogenic factors and NF-κB in colon cancer cells." (PMID 31108984, 2019). "In colon cancer, mutation of the APC tumor suppressor activates β‐Catenin/Tcf signaling, leading to transcriptional induction of c‐myc and cyclin D1 in colon cancer 13, 15 illustrating the oncogenic potential of this signal transduction pathway." (PMID 30869835, 2019). "Since our data demonstrated that uL3 status influences Cyclin D1 levels in colon cancer cells, we proceeded in the attempt to characterize the specific molecular targets of uL3 along the expression process of Cyclin D1." (PMID 31659203, 2019). "The proteins downstream of the STAT3 pathway, including cyclin D1, survivin and c-myc, also decreased correspondingly in all three colon cancer cell lines." (PMID 30736824, 2019). "Another study used EP to treat human colon carcinoma HT-29 cells in germinated brown rice, and found a downregulation of cyclin D1, G0/G1 arrest, as well as caspase-3 activation." (PMID 30544579, 2018). "It has been reported that PDCD4 knockdown stimulates cell proliferation by up-regulating the cyclin D1 expression in HT29 colon carcinoma cells and keratinocytes." (PMID 30687637, 2018). "Of these compounds, the G2/M arrest of cordycepin, which regulated cyclin D1, cyclin B1 and p21 protein, has been investigated in melanoma, bladder and colon cancer cells." (PMID 29522490, 2018). "Hydrophobic and hydrophylic fractions decreased cell proliferation in human colon cancer cells through a decrease of Cyclin D1 and p21." (PMID 30190788, 2018). "Celecoxib inhibits Wnt/β-catenin signaling pathway and its genes products survivin and cyclin D1 there by it shows chemopreventive effects against colon cancer." (PMID 30096840, 2018). "In this study, reduction of cyclin D1 observed in colon carcinoma cells, however, was attributed to vitamin E or tocotrienol content." (PMID 28210630, 2017). "Cyclin D1 overexpression leads to increased proliferation, angiogenesis and cell survival, which are essential to maintain the malignant phenotype in colon cancer." (PMID 28414818, 2017). "MiRNA targeting (miR-577) of E2F3 was found to inhibit gastric cancer cell progression, and miRNA targeting of E2F3 and CCND1 (miR-449b) was found to inhibit the proliferation of SW1116 colon cancer stem cells." (PMID 28589857, 2017). "Altogether these results suggest that Sdc1 loss promotes colonic tumor growth through augmented intestinal inflammation, activation of IL6-STAT3 signaling axis, and subsequent induction of Cyclin D1 and other pro-cancerous effectors." (PMID 28350804, 2017). "Another study found miR-449b acts as a tumor suppressor in colon cancer stem cells through CCND1 and E2F3 down-regulation." (PMID 28821833, 2017).
colon carcinoma (continued). "Our previously published studies also revealed InsP6 stimulated down-regulation of the expression of cyclin D1 in colon cancer cells." (PMID 28972559, 2017). "HuR has been advocated to regulate mRNA stabilization of oncogenic transcripts, including β-catenin, cyclin D1, and c-Myc, which are crucial in Wnt-activated pathway in colon cancer cells." (PMID 28968471, 2017). "In line, decreased cyclin D1 mRNA stability and induction of G0/G1 growth arrest has been reported in colon cancer in response to SAHA treatment." (PMID 29100385, 2017). "A recent study reported that LPP3 does not promote tumor formation but amplifies β-catenin signaling and cyclin-D1 activity to potentiate the growth of SW480 colon carcinoma." (PMID 27895803, 2016). "In this work, we have analyzed by immunohistochemistry the localization of Ccnd1 in endometrial, breast, prostate and colon carcinomas with different types of invasion." (PMID 27105504, 2016). "It was reported that SAHA exposure up-regulated the expression of Cyclin D1 in colon cancer cells and mantle cell lymphoma cells." (PMID 27447743, 2016). "For cyclin D1, a transcriptional down-regulation was observed in a time-dependent manner following treatment of colon cancer cells with 108 or 109 CFU/mL bacteria." (PMID 26849051, 2016). "This negative regulation is accomplishing by directly reducing CCND1 to inhibit proliferation, invasion and migration in colon cancer cells." (PMID 27191497, 2016). "Together these findings indicate that miR-374a inactivates the PI3K/AKT axis by inhibiting CCND1, suppressing of colon cancer progression." (PMID 27191497, 2016). "We next examined the expression of miR-374a and CCND1 in 90 colon tumor tissues by in situ hybridization (ISH) and immunohistochemistry (IHC) respectively." (PMID 27191497, 2016). "For example, Kaiso represses cyclin D1 expression by binding to CCND1 promoter in a sequence- and methyl-CpG-specific manner in breast and colon cancer." (PMID 27411336, 2016). "Butyrate reduces the development of colon cancer by reducing the expression of vital genes, cyclin D1 and c-myc." (PMID 27994577, 2016). "In colon carcinoma cells, RORα was shown to bind β-catenin directly and inhibit β-catenin-mediated transcriptional activation of the target genes, cyclin D1 (CCND1) and c-myc (MYC), resulting in repression of cell proliferation and migration." (PMID 26878025, 2015). "The mechanism of SFN on human colon carcinoma HT-29 cells was reported to be mediated via inducing expression of p21CIP1 and cyclin D1 through activating the MAPK pathways, including ERK, JNK and p38." (PMID 26694491, 2015). "Wnt signaling activates the TCF/LEF family to promote a progenitor-like gene expression signature (c-Myc and cyclin D1) and is a common pathway that is deregulated in most colon cancers." (PMID 26167492, 2015). "Our findings demonstrated that brewers’ rice downregulates β-catenin and the Wnt target proteins cyclin D1 and c-myc, which provides a good rationale for a further comprehensive study of dietary brewers’ rice against colon cancer." (PMID 26122204, 2015). "Here we report that resibufogenin induces G1-phase arrest with hypophosphorylation of retinoblastoma (RB) protein and down-regulation of cyclin D1 expression in human colon cancer HT-29 cells." (PMID 26121043, 2015). "Our results were consistent with these findings, suggesting that miR-506-EZH2 promotes the proliferation of colon cancer cells by regulating p21 and cyclin D1." (PMID 26452129, 2015). "The cyclin D1 coding gene CCND1 is also a target gene of the Wnt/β-catenin pathway, which was described in colon cancer cells." (PMID 26798342, 2015). "Ectopic overexpression of KLF5 indeed stimulated proliferation of normal intestinal epithelium through activation of CCND1, yet in colon cancer cells, proliferation and colony formation capacity were reduced through failure of KLF5 to induce CCND1." (PMID 24429391, 2014).
colon carcinoma (continued). "And further analysis indicated that CCND1 was negatively regulated by miR-365 like the targeting mechanism in gastric and colon cancers." (PMID 24949940, 2014). "We show that T-Antigen and β-catenin co-localize in the nucleus of colon cancer cells in vitro and interact to enhance the activation of the β-catenin target genes c-Myc and Cyclin D1." (PMID 25229241, 2014). "Further, SPDEF inhibited the expression of β-catenin-target genes in mouse colon tumors, and interacted with β-catenin to block its transcriptional activity in colorectal cancer cell lines, resulting in lower levels of cyclin D1 and c-MYC." (PMID 24472151, 2014). "Herein we demonstrate a relationship between JCV T-Antigen and β-catenin in human colon cancer cases and we elucidate the effects of this interaction in vitro on the activation of the β-catenin target genes c-Myc and Cyclin D1." (PMID 25229241, 2014). "In both gastric and colon cancers, miR-365 targeted Cyclin D1 (CCND1) to inhibit cell cycle progression to repress tumorigenesis." (PMID 24949940, 2014). "A further study found that maoecrystal I decreased the expression of Wnt signaling target genes, including c-myc, cyclin D1, survivin and Axin2 in colon cancer cells." (PMID 24955294, 2014). "Cyclin D1 is a known cell cycle protein that is frequently over-expressed in human colon cancer and plays a prominent role in driving tumorigenesis." (PMID 23844215, 2013). "We next evaluated the expression of the Kaiso target gene cyclin D1 that has been shown to drive proliferation in the intestinal epithelium and is frequently overexpressed in colon cancer." (PMID 24040197, 2013). "Previous reports have shown that galectin-3 mediates nuclear β-catenin accumulation and subsequently increases TCF4 transcriptional activity followed by the upregulation of its target genes, such as cyclin D1 and c-myc, in colon cancer cells." (PMID 24303084, 2013). "SFRP-1 and the SFRP-like molecule V3Nter can inhibit Wnt signaling and expression of the β-catenin target genes - cyclin D1 and c-myc, finally inhibiting tumor growth of β-catenin-activated tumor cells such as colon cancer SW480 and HCT-116 cells." (PMID 23469066, 2013). "DIXDC1, the human homolog of Ccd1, is a positive Wnt signaling pathway protein that functions downstream of Wnt and upstream of axin and that targets p21 and cyclin D1 to promote colon cancer cell proliferation." (PMID 23667667, 2013). "As a first step toward examining Kaiso’s potential role in cell cycle regulation we examined cyclin D1 protein levels by western blot analysis of Kaiso-depleted HCT 116 colon carcinoma cell lysates." (PMID 23226276, 2012). "We also measured Cyclin D1 levels because SF can induce G1 cell cycle arrest by inhibiting expression of Cyclin D1 in human colon carcinoma HT-29 cells." (PMID 23251470, 2012). "Cyclin D1 expression is downregulated by PKCδ in colon cancer cells, as well as in PKCδ overexpressing vascular smooth muscle cells, primary bovine airway smooth muscle cells, and NIH3T3 cells." (PMID 23335926, 2012). "The apoptosis index was increased and the expression of key proliferation markers cyclin D1 and c-Myc were downregulated in test colon tumors, providing good in vivo molecular evidence for the antiproliferative efficacy and associated antitumor activities." (PMID 23024755, 2012). "BC21 blocks the clonogenic activity of colon cancer cells, down-regulates c-Myc and cyclin-D1 expression, and represents a new potential anticancer agent that targets TCF4/beta-catenin interaction." (PMID 22910040, 2012). "Cyclin D1 is a direct target for the β-catenin/Tcf complex, and plays a crucial role in proliferation of colon cancer cells." (PMID 22651859, 2012). "siRNA-treatment resulted in a strong reduction of EZH2 levels in all tested colon carcinoma cell lines and, as previously reported for other cells, in a concomitant decrease of cyclin D1 expression." (PMID 21765901, 2011).